PTX3 (pentraxin 3)
Diseases named in the same sentence as PTX3 in open-access papers (continued):
Sharing a sentence is not in itself a finding about the gene and the disease.
metabolic syndrome (24 papers, 2013 to 2025). A cluster of metabolic risk factors for CARDIOVASCULAR DISEASES and TYPE 2 DIABETES MELLITUS. "In another study, increasing PTX3 levels were associated with metabolic syndrome indicators, including abdominal obesity." (PMID 37240630, 2023). "PTX3 associated inversely with the total number of metabolic syndrome components in all individuals (n = 779) after adjustment for age, sex, and smoking." (PMID 24705587, 2014). "Non-diabetic patients (n = 655) showed a stronger inverse association between PTX3 and total number of metabolic syndrome components." (PMID 24705587, 2014). "Various features associated with metabolic syndrome correlate negatively with PTX3 levels but positively with CRP." (PMID 24705587, 2014). "Although the functional role of PTX3 in tumor progression and metabolic disorders has been demonstrated, the impact of PTX3 on dyslipidemia-associated tumor metastasis remains unknown." (PMID 28489600, 2017). "Additionally, plasma PTX3 levels correlated inversely with variables associated with metabolic syndrome, including BMI, waist circumference, and triglycerides, while positively correlating with HDL cholesterol after adjustment for age." (PMID 24705587, 2014). "However, the impact of long pentraxin-3 (PTX3) on dyslipidemia-associated tumor metastasis remains unknown." (PMID 28489600, 2017). "Pentraxin-3 is a protein mediator of innate immunity produced by VSMCs and ECs and observed predominantly in patients with impaired diastolic function, metabolic syndrome, myocarditis and chronic HF." (PMID 33663396, 2021). "PTX3 was correlated with inflammation, dyslipidemia, and renal function, illustrating that multiple influential factors are involved." (PMID 32078718, 2020). "Elevated plasma PTX3 levels are associated with the presence of fibrosis in patients with NAFLD, independently of metabolic syndrome components." (PMID 26997950, 2016). "PTX3 at 5-year follow-up was inversely correlated with multiple metabolic risk factors for CVD, including body composition, arterial stiffness, dyslipidemia and previous GDM." (PMID 26842615, 2016). "In summary, elevated plasma PTX3 levels are associated with the presence of fibrosis in patients with NAFLD, independently of metabolic syndrome components and fibrosis predictors." (PMID 26997950, 2016). "Individuals with metabolic syndrome had lower PTX3 levels (mean = 3.89 ng/mL, SE = 0.10, n = 397) than those without metabolic syndrome (4.22 ng/mL, SE = 0.10, P = 0.02, n = 382), after adjustment for age, sex, and smoking." (PMID 24705587, 2014). "Although the present study offers clinical evidence that further links PTX3 with metabolic syndrome, understanding the biology of this immunomodulator in cardiometabolic disorders requires additional multidisciplinary investigations." (PMID 24705587, 2014). "Plasma PTX3 was induced in patients with the metabolic syndrome." (PMID 32078718, 2020). "The inhibition of PTX3 could be a potential strategy for the treatment of dyslipidemia-mediated HNSCC metastasis." (PMID 28489600, 2017). "Overall, PTX3 levels correlated inversely with the number of metabolic syndrome components." (PMID 24705587, 2014). "Although our results demonstrate that plasma PTX3 levels associate inversely with components of metabolic syndrome, the study does not support a relation between this pentraxin and recurrent CHD risk, unlike other pentraxin family members such as CRP." (PMID 24705587, 2014). "Moreover, non-diabetic individuals showed a significant inverse correlation between PTX3 and the number of metabolic syndrome components." (PMID 24705587, 2014). "Although the study further links low PTX3 levels with various features associated with metabolic syndrome, the results do not indicate that PTX3 can predict recurrent coronary events among MI survivors." (PMID 24705587, 2014).
metabolic syndrome (continued). "In the general population and in disease states including chronic kidney failure and insulin resistance or metabolic syndrome, low plasma PTX3 was found in most reports in obese individuals and in subjects with high waist circumference, despite high PTX3 expression in abdominal fat." (PMID 24215445, 2013). "Also in patients with metabolic syndrome, PTX3 levels were directly correlated with CCA-IMT; this correlation, however, was no longer significant after adjustment for HDL-C levels." (PMID 23690668, 2013). "PCT and PTX-3 levels in diabetic patients have been shown to be higher when compared to non-diabetic controls, and plasma PCT is positively associated with body mass index, insulin resistance, and components of the metabolic syndrome in population-based studies." (PMID 33755703, 2021). "Notably, type 2 diabetes patients with NAFLD had serum PTX3 levels as high as patients with normal liver function illustrating an association of serum PTX3 with dyslipidemia rather than NAFLD." (PMID 32078718, 2020). "As expected, the HC diet induced hyperglycemia and dyslipidemia, lipid accumulation in adipose and liver, and elevated receptor activator of nuclear factor kappa‐Β ligand (RANKL)/osteoprotegerin (OPG) ratio and Pentraxin 3 (PTX3) levels." (PMID 40599131, 2025). "There are no published data on the associations between plasma concentration of pentraxin-3 (PTX-3) - a marker of vascular inflammation and mortality in older subjects with or without metabolic syndrome (MS)." (PMID 40340865, 2025). "Levels of PTX3 are elevated in patients with cardiovascular disease (CVD) and high values in the general population are considered to be predictive of CVD, especially in patients with arterial hypertension and with dyslipidemia." (PMID 26903710, 2016). "PTX3 levels are elevated in patients with CVD, and elevated levels in the general population are considered predictors of CVD, especially in patients with arterial hypertension affected by dyslipidemia." (PMID 26903710, 2016). "PTX3 did not predict CHD risk (nonfatal MI and fatal CHD), even after adjustment for metabolic syndrome components, other coronary risk factors, and medication use." (PMID 24705587, 2014). "As not only PTX3 but also HDL sense changes in the immune response, the possibility that, in patients with metabolic syndrome, changes in PTX3 or HDL-C levels could both reflect similar alterations in the immunoinflammatory profile should not be excluded." (PMID 23690668, 2013). "The measurement of PTX3 expression levels may provide prognostic information for the treatment of HNSCC metastasis, which suggests that PTX3 could be a novel therapeutic target for dyslipidemia-regulated HNSCC metastasis." (PMID 28489600, 2017). "Thus, additional follow-up of patients with genetically determined dyslipidemia and CAD is required, with well-planned, continuous, long-term treatment to further investigate the therapeutic potential of lowering PTX3 directly or through gene-silencing treatments." (PMID 26903710, 2016). "HDL induces PTX3 mRNA expression and protein release in human endothelial cells through activation of the PI3K/Akt pathway, which may contribute to low plasma PTX3 levels in individuals with metabolic syndrome who have low HDL levels." (PMID 24705587, 2014). "In the current study, we have demonstrated that PTX3 levels in NAFLD patients with fibrosis were higher than NAFLD patients without fibrosis and healthy subjects, independent of metabolic syndrome components." (PMID 26997950, 2016).
pancreatic cancer (24 papers, 2014 to 2025). "The authors proved that high serum PTX3 was an independent risk factor for visceral fat loss, decreased skeletal muscle mass index, and poor prognosis for pancreatic cancer patients." (PMID 38136377, 2023). "Other papers also confirmed that PTX3 expression is upregulated in activated pancreatic stellate cells and can be used as a potential diagnostic biomarker for pancreatic cancer." (PMID 38136377, 2023). "Overexpression of PTX3 has been related to poor prognosis in pancreatic cancer and is linked to more advanced stages of the disease." (PMID 34917682, 2021). "In pancreatic carcinoma, high PTX3 levels were associated with advanced clinical stage and poor overall survival." (PMID 31019517, 2019). "The current review study identifies 22 IHC biomarkers as diagnostic tools for pancreatic cancer that embrace: Pentraxin-3, ENO1, REG4, POSTN, CA125, CA242, Galectin-1, Galectin-9, Maspin, pVHL, MUC1, MUC5AC, THBS2, LTBP2, CPA4, IMP3, CD13, Dkk1, KOC, S100P, Mesothelin, PAM4." (PMID 34988027, 2021). "Moreover, high PTX3 levels were associated with advanced clinical stage and poor overall survival of patients with pancreatic carcinoma." (PMID 32345771, 2020). "In pancreatic cancer, a positive correlation has been observed between high PTX3 expression and inflammatory markers, including serum CRP and IL-6 levels." (PMID 39594709, 2024). "The authors also confirmed a strong correlation between pentraxin 3 expression and the prognosis of pancreatic carcinoma." (PMID 38136377, 2023). "PTX-3 is secreted and expressed in case of pancreatic cancer by pancreatic stellate cells (believed to be the precursors of carcinoma)." (PMID 36499628, 2022). "The regulation of matrix deposition and angiogenesis through PTX-3 in pancreatic cancer remains to be elucidated." (PMID 36499628, 2022). "PTX3 has been suggested to play a significant role in cancer-related inflammation and was shown to be increased in lung, prostate, ovarian, liver, and pancreatic carcinomas." (PMID 36555812, 2022). "For example, high expression of PTX3 was observed in pancreatic cancer, and there was a strong correlation between the prognosis of pancreatic cancer patients." (PMID 33952272, 2021). "For example, a high expression of PTX3 was found in pancreatic cancer cell lines and a direct relationship was found between tumor metastasis and PTX3 expression." (PMID 31334115, 2019). "PTX3 levels were significantly higher in serum samples of PDAC patients, indicating that PTX3 may be a specific biomarker for pancreatic cancer." (PMID 38520221, 2024). "Interestingly, we also found a paper concerning Pentraxin 3 as an adipose tissue-related serum marker for pancreatic cancer cachexia." (PMID 38136377, 2023). "For two of these proteins, Laminin-C2 and Pentraxin-3, the plasma levels were significantly higher in patients than in healthy donors, and their good laboratory performance makes them two promising biomarkers of pancreatic cancer." (PMID 35681634, 2022). "Treatment of mice xenografted with human pancreatic cancer with A platensis led to an underexpression of endothelin 1, pentraxin 3 and acidic fibroblast growth factor and an overexpression of 3 angiogenic proteins in tumours, including VEGF‐A and AREG acting via VEGFR or EGFR." (PMID 31957261, 2020). "However, a high PTX3 expression has been proved to be related to pancreatic cancer metastasis." (PMID 33967610, 2021). "Furthermore, PTX3 has previously been shown to induce the migration of pancreatic cancer cells." (PMID 32146560, 2020). "PTX-3 is able to ensure migratory potential of malignant cells by stimulating their epithelial–mesenchymal transition (EMT), a mechanism also seen in pancreatic cancer cells." (PMID 36499628, 2022). "In conclusion, pancreatic tumors release LAMC2 and PTX3, which can be quantified in the systemic circulation, and may be useful in selecting patients for further diagnostic imaging." (PMID 35681634, 2022).
pancreatic cancer (continued). "In vitro screening of a panel of pancreatic cancer cell lines and immortalized pancreatic stellate cells (PS1) showed the PTX3 monomer (45 kDa) to be expressed and secreted predominantly by PSC and the antibody specificity was confirmed upon PTX3 RNAi." (PMID 34188166, 2021). "Specifically, pentraxin-3 can discriminate pancreatic cancer from gallstone disease; maspin and pVHL may discriminate pancreatic cancer from mucinous cystic pancreatic neoplasms; THBS2 may differentiate between pancreatic cancer and intraductal papillary mucinous pancreatic neoplasms." (PMID 34988027, 2021).
Hypertension (23 papers, 2014 to 2025). The presence of chronic increased pressure in the systemic arterial system. "Hypertension (OR 6.91), PTX3 (OR 1.47), and ACE I/I polymorphism (OR 0.09) are significant predictors of poor outcomes." (PMID 39062191, 2024). "PTX3 rs3816527 genotypes have been shown to confer the predisposition to numerous conditions, including microbial infection, hypertension, migraine, and oral malignancy." (PMID 39187920, 2024). "In the multivariate regression model, important predictors of death were hypertension and PTX3, while ACE I/I polymorphism reduced the probability of death." (PMID 39062191, 2024). "In the multivariate regression analysis, only hypertension, PTX3, and ACE D/D polymorphism remained important predictors of the severity of CXR infiltrates." (PMID 39062191, 2024). "Significant independent predictors of severe CXR infiltrates include hypertension (OR 7.71), PTX3 (OR 1.20), and ACE D/D polymorphism (OR 18.72)." (PMID 39062191, 2024). "Plasma PTX3 remained statistically significant in association with BMI (P trend <0.001) and waist circumference (P trend <0.001) even after adjustment for age, sex, smoking, history of hypertension, triglycerides, HDL cholesterol, and insulin." (PMID 24705587, 2014). "In addition to well established risk factors such as diabetes, hypertension, dyslipidemia, recent evidence indicates that as it occurs for molecules belonging to the acute phase of inflammation, PTX3 may play a key role in the onset and progression of CVD." (PMID 27559355, 2016). "Taken together, the present study suggests that PTX‐3 is involved, at least as a mediator, in response to endothelial activation and the establishment of hypertension in SHR." (PMID 39414396, 2024). "Despite some discordant results, circulating PTX‐3 concentration has been shown to be elevated in patients with hypertension." (PMID 39414396, 2024). "Age, blood pressure, blood urea nitrogen, creatinine, C-reactive protein, soluble thrombomodulin, pentraxin 3, frequency of hypertension, hematuria, and proteinuria were significantly higher in patients with AAV than in the controls." (PMID 35160215, 2022). "After 12 weeks of EOJ consumption, four genes related to hypertension (PTX3, NLRP3, NPSR1 and NAMPT) were differentially expressed in peripheral blood mononuclear cells (P < 0.05)." (PMID 32661681, 2021). "In the simultaneous analysis, the first of three regressions shows that PTX3 negatively associates with BMI, CRP, and history of CVD hypertension included, suggesting that PTX3 is modulated by several aging conditions and/or disorders." (PMID 28536575, 2017). "However, the role of increased physiological concentration of PTX‐3 on the development of LVH in hypertension still requires elucidation." (PMID 39414396, 2024). "In addition to the lack of consensus, both studies used supraphysiological concentration of PTX‐3 leaving a gap on the effect of physiological level of PTX‐3 (circulating or myocardial) on the development of concentric LVH in hypertension." (PMID 39414396, 2024). "Therefore, the current study highlights the role of circulating and LV‐specific expression of PTX‐3 in the development of hypertension‐induced concentric LV remodeling." (PMID 39414396, 2024). "However, vasculitis with hypertension had higher levels of pentraxin-3 than those with essential hypertension or healthy subjects." (PMID 36292253, 2022). "Pulmonary diseases including CTEPH and PAH are distinct from hypertension but could have an inflammatory condition similar to that in hypertension (e.g., elevation of Pentraxin 3 level)." (PMID 34103026, 2021). "Moreover, circulating levels of PTX3 were found to be increased in hypertensive patients, leading us to candidate PTX3 as a novel prognostic marker for arterial hypertension." (PMID 30733816, 2019).
Hypertension (continued). "Interestingly, PTX-3 has been suggested as a novel biomarker of hypertension, which is a common toxic effect of bevacizumab that is associated with improvement of the anti-angiogenic treatment effect." (PMID 30592740, 2018). "PTX‐3, a pro‐inflammatory mediator released during tissue injury, may be involved in endothelial activation, an important mechanism in the establishment of hypertension." (PMID 39414396, 2024). "Our study highlights the involvement of PTX‐3 in the development of hypertension but not in the development of LVH using the differential effects of captopril and hydralazine in SHR." (PMID 39414396, 2024). "In this regard, studies elucidating the context‐specific functions of PTX‐3 and exploring its crosstalk with other inflammatory mediators in the setting of hypertension are lacking." (PMID 39414396, 2024). "We also showed that circulating PTX‐3 and VCAM‐1 concentrations were elevated with hypertension." (PMID 39414396, 2024). "RHI was not related to s-PTX3 in analyses adjusted for age, gender, IRD and traditional CV risk factors (smoking, BMI, hypertension, hyperlipidemia and hypercholesterolemia)." (PMID 28225768, 2017). "As our study did not measure IL-6 and PTX-3, directly assess endothelial function, or stratify patients based on hypertension status, we could not explore these potentially important differential inflammation patterns." (PMID 40428013, 2025). "PTX‐3 may not be involved in the development of LVH in SHR, but plausibly reflects the localized inflammatory milieu associated with hypertension." (PMID 39414396, 2024). "Recent evidence suggests that markers such as interleukin-6 (IL-6) and pentraxin-3 (PTX-3) are elevated in patients with obstructive sleep apnea (OSA), even in the absence of hypertension." (PMID 40428013, 2025).